LEP (leptin)
Diseases named in the same sentence as LEP in open-access papers (continued):
Sharing a sentence is not in itself a finding about the gene and the disease.
Obesity (continued). "Rodent models of obesity based on mutations in leptin-coding gene (Lepob/Lepob) have shown thymic involution that reduces T cell responses and the number of T cell emigrants to the periphery." (PMID 26336514, 2015). "Obesity and pregnancy are leptin resistant states associated with impaired leptin signalling in the hypothalamus." (PMID 26110385, 2015). "Obesity was induced by the obese (ob) mutation in the lep gene coding for the hormone leptin, or by a 45% fat diet." (PMID 26347815, 2015). "Increases in tumor necrosis factor- α (TNF- α) and serum leptin levels with aging have been associated with obesity and atherosclerosis." (PMID 26473487, 2015). "Leptin is used in the treatment of hypoleptinemiadue to energy deprivation state, leptin deficiencyand obesity-related hyperleptinemia." (PMID 26246872, 2015). "It is associated with a marked increase in circulating leptin concentrations (Ob gene product) but the pathophysiological mechanisms linking obesity and CVD are poorly defined." (PMID 25762868, 2015). "In general, obese animals have higher leptin levels than controls, indicating that these forms of animal obesity are associated with leptin resistance." (PMID 25797953, 2015). "The loss of leptin signaling, in addition to causing extreme obesity, also results in metabolic alterations that include diminished brown fat mediated thermogenesis, rendering ob/ob mice hypothermic." (PMID 25849936, 2015). "Serum levels of leptin are strongly associated with fat mass, BMI and leptin resistance in obesity and also tend to increase in diabetes, hypertension, hyperlipidemia, and ischemic heart disease." (PMID 26003803, 2015). "In cross-sectional studies, leptin levels have been associated with IR and the proinflammatory state that accompanies obesity." (PMID 24736687, 2014). "We report evidence of a detailed epigenetic modification of the leptin promoter and the effects of n-3 polyunsaturated fatty acids (n-3 PUFAs), which is closely associated with the leptin gene transcription in obesity." (PMID 24923522, 2014). "In humans, obesity is associated with high circulating leptin levels probably reflecting a state of leptin resistance, i.e. impaired leptin signalling and action." (PMID 25276234, 2014). "Other mediators associated with oncogenesis such as hyperinsulinemia and a high leptin:adiponectin ratio were elevated by obesity and reduced with weight loss." (PMID 25072025, 2014). "Hyperglycemia in the ob/ob mouse is probably caused by leptin deficiency, and its limited severity is due to sustained hyperinsulinemia, which leads to obesity as a side effect." (PMID 24809394, 2014). "Although this is the first study describing the effect of central leptin on TH expression in a diet-induced obesity model, our results coincide with findings of leptin-deficient ob/ob mice and leptin receptor-deficient obese Zucker rats." (PMID 24498181, 2014). "Leptin is a 167 amino acid protein encoded by the obesity (OB) gene and is synthesized and secreted by adipocytes." (PMID 24981337, 2014). "We tried to assess trace elements status [zinc (Zn), copper (Cu), selenium (Se), iron (Fe), and chromium (Cr)] in obese Egyptian children and their relationships with serum leptin and metabolic risk factors of obesity." (PMID 24555483, 2014). "Though fructose has been linked to obesity in several animal models, our data fail to support a role for fructose intake through food lasting 3 months in altering of body weight and leptin signaling in mice." (PMID 25211467, 2014). "We also intended to clarify the possible associations between chemerin levels and various markers of obesity, including lipid profile, high-sensitivity C-reactive protein (hsCRP) and classical adipokines such as leptin and adiponectin in these patients." (PMID 24702860, 2014).
Obesity (continued). "Leptin-deficient mice develop obesity and cardiac remodeling which is completely reversed by leptin infusion, suggesting that leptin itself has cardiac anti-hypertrophic bioactivity." (PMID 25113792, 2014). "In the context of obesity, we found a relationship between gray and white matter brain regions associated with a higher amount of body fat as measured by the serum leptin concentration." (PMID 25494174, 2014). "With the increasing incidence of both obesity and thyroid cancer, we designed the present study to investigate a causal relationship between leptin, which is one of the well known adipokines, and well-differentiated thyroid cancer (WDTC)." (PMID 24867470, 2014). "Leptin, a product of OB gene, is produced in adipose tissues and has a long list of endocrine functions besides being responsible for causing obesity." (PMID 25587271, 2014). "The present study provides clinical evidence that leptin is associated with vascular endothelial function in T2D patients with moderate obesity." (PMID 24410779, 2014). "Some cases of obesity, like those due to mutations in the leptin gene, can be treated with leptin replacement." (PMID 24701352, 2014). "Our results suggest that obesity influences cardiovascular risk primarily through changes in leptin and resistin and less efficiently at the level of adiponectin." (PMID 24736687, 2014). "High-fructose diets have been implicated in obesity via impairment of leptin signaling in humans and rodents." (PMID 25211467, 2014). "Since insulin and leptin are strongly associated with increases in obesity, it is plausible that there is a cross over from peripheral circulation to the reproductive tract." (PMID 24885899, 2014). "A detailed comparison of the roles of genetic susceptibility, obesity, hyperglycemia, hyperinsulinemia, insulin resistance, and diabetic complications as well as leptin expression, signaling, and other factors that confound translation are presented here." (PMID 24809394, 2014). "Up to now, several mutations like R105W, N103K, and L72S in LEP have been reported to be related with a phenotype of extreme obesity around the world." (PMID 24707501, 2014). "By utilising models of type 2 diabetes and obesity with a common underlying defect in leptin signalling, we were able to directly address the influence of hyperglycaemia." (PMID 25496763, 2014). "Obesity in rats caused by alterations in hypothalamic arcuate nucleus and impairs leptin and insulin signaling in this region resulting in hyperleptinemia and hyperinsulinemia." (PMID 25030027, 2014). "Several studies have shown that increased circulating leptin levels and increased adiposity are associated with leptin resistance and that this condition can contribute to the onset and/or maintenance of obesity." (PMID 24729662, 2014). "Our finding that a HFD impaired cardiac vagal modulation contrasts with previous observations of mice with diet-induced obesity, but fits well with data from obese humans and our own data from leptin-deficient obese mice." (PMID 24950219, 2014). "Obesity in these models is primarily due to uncontrolled appetite, hyperphagia, and reduced energy expenditure, which are directly caused by leptin signaling abnormalities." (PMID 24809394, 2014). "Adipose tissue-secreted proteins (or adipokines) such as leptin and adiponectin have been implicated as mediators in the pathogenesis linking obesity to cancer risk." (PMID 25115836, 2014). "We demonstrated that obesity is associated with increased levels of C-peptide, leptin, insulin, GLP-1, PYY, and glucagon." (PMID 25309773, 2014). "Leptin is closely linked to obesity and its complications, especially metabolic syndrome, diabetes mellitus, and CVD." (PMID 24825928, 2014). "The obesity-linked adipokine, leptin, is a well-known mitogen/survival factor in breast cancer cells, and has been shown to upregulate hepatic LSR levels and ultimately control of hepatic uptake of lipids in vivo." (PMID 24637461, 2014).
Obesity (continued). "Potentially, the infant of the obese mother, who is ingesting an increased amount of leptin, becomes leptin resistant and subsequently has impaired appetite regulation, with an increased risk of obesity." (PMID 25536196, 2014). "The intake of milk leptin during the suckling period is thought to improve leptin and insulin sensitivity in adulthood, reducing the risk of obesity and related health complications, such as cardiovascular diseases and diabetes." (PMID 28234329, 2014). "Whilst studies investigating the association between CRP and adiposity are widespread in various populations, the association between leptin and obesity appears to be more complex." (PMID 24944619, 2014). "We conclude that obesity is a risk factor for osteoarthritis and that physical activity and changes in diet composition can reverse the inflammatory and leptin resistance, reducing progression or preventing the onset of osteoarthritis." (PMID 25184806, 2014). "Obesity is the primary phenotypic manifestation observed in the various leptin- and leptin receptor-deficient rodents, but they also display some T2DM-like characteristics such as hyperglycemia, glucose intolerance, and elevated plasma insulin." (PMID 24809394, 2014). "Congenital leptin deficiency caused by homozygous mutations in the leptin gene results in impaired satiety, intense hyperphagia, and extreme early-onset obesity accompanied by multiple metabolic, hormonal, and immunological abnormalities." (PMID 26567097, 2014). "Impaired leptin signalling associated with extreme obesity induces alterations in subchondral bone morphology but without increasing the incidence of OA." (PMID 24741591, 2014). "For instance, obesity is associated with altered levels of circulating biomarkers, including leptin, ghrelin, and brain derived neurotrophic factor (BDNF), among others." (PMID 25984353, 2014). "Such association concurs with epidemiological studies showing that sleep loss is associated with increased obesity, increased appetite, and elevated leptin levels in adults, and with similar recent findings in children." (PMID 24991089, 2014). "Given the involvement of leptin in such diverse biological effects, leptin resistance and obesity are frequently associated with other diseases such as autoimmunity, some cancers, cardiovascular, and neurodegenerative diseases." (PMID 25352831, 2014). "In this study, we aimed to screen the potential mutations in LEP in obese patients with BMI ≥32 kg/m2 to explore the mechanism of severe obesity in these patients." (PMID 24707501, 2014). "Our previous data have shown that obesity increases B16 melanoma growth in obese leptin-deficient ob/ob mice consistent with other reports." (PMID 24587106, 2014). "Circulating leptin levels rise in proportion to white adipose tissue mass; higher levels are associated with obesity and lower levels with fasting and malnutrition." (PMID 25050734, 2014). "Individuals with homozygous loss-of-function mutations in the genes encoding leptin and the leptin receptor have a normal birthweight but exhibit rapid weight gain in the first few months of life resulting in severe obesity." (PMID 25154910, 2014). "Mice carrying one or more Adcy3Jll mutant alleles are protected from high fat diet-induced obesity, are more active, and have lower circulating leptin and insulin levels." (PMID 25329148, 2014). "Nevertheless, obesity is associated with increased leptin levels and it has been postulated that the apparent decrease in anorexigenic effects and weight loss are the result of a mechanism of resistance to it." (PMID 25548896, 2014). "It has long been known that impairment in leptin signaling causes obesity, increased food intake and fat deposition." (PMID 25386150, 2014). "The close relationship between adiposity and leptin levels suggests that this hormone plays a role in the increased incidence of obesity-associated cancer." (PMID 25019059, 2014).
Obesity (continued). "It should also be noted that increased leptin has been associated with obesity as well as promoting breast cancer growth and increasing angiogenesis [the formation of new blood vessels]." (PMID 25222131, 2014). "Subsequent identification that leptin and its receptor were mutated in rare forms of monogenic human obesity validated the importance of these models." (PMID 24997067, 2014). "Of all monogenic forms of obesity, the only one causally treatable is congenital leptin deficiency caused by homozygous mutations of the leptin gene." (PMID 26567097, 2014). "Obesity is associated with increased serum and seminal insulin and leptin in a cohort of male participants." (PMID 24885899, 2014). "Among the most widely used animal models in obesity-induced type 2 diabetes mellitus (T2DM) research are the congenital leptin- and leptin receptor-deficient rodent models." (PMID 24809394, 2014). "Obesity was also associated with increased levels of leptin, insulin, glucagon, GLP-1, PYY, and C-peptide in overweight and obese chimpanzees." (PMID 25309773, 2014). "Some monogenic forms of obesity have been described (e.g., mutations of leptin and leptin receptor, pro-opiomelanocortin and melanocortin-4-receptor genes) but they are very rare and not sufficient to explain the worldwide distribution of this disorder." (PMID 25386150, 2014). "In summary, adiponectin and leptin levels in elderly patients with T2DM seem to be closely linked to obesity and to length of the disease." (PMID 25105135, 2014). "According to a recent study of our group, adiponectin and leptin levels in T2DM patients are more associated with obesity and less with diabetes." (PMID 25105135, 2014). "The discovery and isolation of the human obesity gene and its protein product, leptin, have furthered our understanding of the role of this peptide in the pathogenesis of obesity-associated diseases." (PMID 24441571, 2014). "Apparently, such a relationship of leptin with AH is associated with the sympathetic nervous system, and its activation accompanies obesity in humans." (PMID 24981337, 2014). "Obesity is associated with alterations in leptin regulation; chronic overexpression of leptin induces leptin resistance, resulting in enhanced levels of circulating leptin." (PMID 25019059, 2014). "Not only has leptin been associated with obesity, but it has also been demonstrated to increase levels of cytokines such as IL-6 and IL-1b, cytokines that were also elevated in our study." (PMID 24732966, 2014). "There are several postulated causes of increased TSH levels in obesity, including autoimmune status, leptin levels, and inflammatory factors." (PMID 25214835, 2014). "Disruption of Lepr selectively in these cells blocks thermogenic responses to leptin and causes obesity." (PMID 25176149, 2014). "Genetic deficiency of leptin or functional leptin receptors also results in obesity and obesity-associated metabolic diseases in both animals and humans." (PMID 24987707, 2014). "Obesity and hyperleptinemia caused by diet lead to impaired leptin-induced NO and cyclic guanosine monophosphate production in the aortic wall of rats and in aortic endothelial cells of mice." (PMID 24410779, 2014). "Obesity causes an increase in the synthesis of proinflammatory adipokines, such as leptin, and a decrease in the production of anti-inflammatory adipokines, which results in the development of a chronic, low-grade inflammatory state." (PMID 25136363, 2014). "Obesity is related to higher levels of circulating leptin reflecting, in part, an increased formation of adipocytes, and causing leptin resistance in some obese subjects." (PMID 24762259, 2014). "According to these data, during weight loss, circulating leptin levels and obesity-associated inflammatory markers are reduced." (PMID 25548896, 2014). "Further, human congenital leptin deficiency is associated with early-onset obesity, which can be effectively treated with leptin-replacement therapy." (PMID 26237477, 2014).
Obesity (continued). "For instance, leptin (an important adipokine acts on receptors in the hypothalamus of the brain where it inhibits appetite) resistance has been known to cause obesity and interestingly ER stress has been found to induce leptin resistance." (PMID 25120434, 2014). "This is complicated, however, by the fact that both the leptin-deficient and leptin receptor-deficient ob-/- and db-/- mice, respectively, still develop insulin resistance in the setting of genetic obesity." (PMID 25157251, 2014). "Adipocytokines, such as adiponectin and C-reactive protein, and leptin are inflammatory proteins that have been linked to obesity and type 2 diabetes." (PMID 25208549, 2014). "By that approach, a mutant gene responsible for extreme obesity in the ob/ob mouse was cloned and shown to encode leptin, an anorexigenic peptide secreted from the adipocyte." (PMID 24752583, 2014). "Another obesity-associated factor that can contribute to the increased local production of leptin and subsequent pro-tumorigenic effects is AT hypoxia." (PMID 25360510, 2014). "Chronic hyperleptinemia either induced in lean rats by administration of exogenous hormone or “endogenous” hyperleptinemia associated with obesity induced by highly palatable diet impairs acute vascular NO-mimetic effect of leptin." (PMID 25521118, 2014). "Aside from mechanical stress, increased circulating levels of obesity-associated hormones, such as sex steroids, insulin, insulin-like growth factor 1, and leptin, are potential pathogenic mediators in obesity-associated lumbar disc degeneration (LDD)." (PMID 24441571, 2014). "In this study, we found HFD fed mice was under the pathophysiologic condition of inflammation associated with obesity evidenced by high levels of IT-6, TNFα and leptin." (PMID 24143244, 2013). "Genetic loss-of-function mutants for leptin or its receptor in mouse models (i.e., ob/ob or db/db mice) develop systemic metabolic abnormalities that include obesity, diabetes, infertility, and immune defects." (PMID 23819063, 2013). "Obesity is characterized by leptin resistance, which is additionally associated with chamber dilatation, dysfunction and increased risk of heart failure." (PMID 24354396, 2013). "Obesity was associated with hyperleptinemia and elevated cardiac leptin expression in both diet-induced and genetically obese mice." (PMID 23841921, 2013). "Leptin is an adipocyte-specific ob gene product that has been found to be associated with insulin resistance and diabetes in obesity patients through insulin sensitivity and insulin secretion alterations." (PMID 24282409, 2013). "Leptin levels were increased, likely reflecting the combined effects of obesity and loss of the MC4R receptor." (PMID 24400148, 2013). "The balance of leptin as well as the adiponectin concentrations are the critical factors in breast cancer risk and in other obesity related cancer genesis." (PMID 23061769, 2013). "Development of diet-induced obesity in WT mice was associated with increased plasma levels of insulin, leptin, cholesterol and triglycerides as compared to Cox6a2−/− mice." (PMID 23460811, 2013). "Despite observations in wild type and ob/ob mice that leptin supplementation decreases feeding and weight gain, there is little evidence to support leptin deficiency as an etiologic factor in sporadic human obesity." (PMID 24533218, 2013). "We have shown that the disruption of these hypothalamic mechanisms, including insulin, leptin, and serotonin systems, is associated with obesity." (PMID 24049658, 2013). "Obesity and obesity-associated hyperleptinaemia caused by leptin resistance have been linked to reproductive disorders in human beings and some animal species like the pig." (PMID 23935823, 2013). "Although current pharmacological and behavioral treatments for obesity cause initial weight loss, this effect is transient and generally followed by weight regain, which is associated with leptin resistance." (PMID 23579596, 2013).